SERINC2 (serine incorporator 2)
Diseases named in the same sentence as SERINC2 in open-access papers (continued):
Sharing a sentence is not in itself a finding about the gene and the disease.
Sepsis (2 papers, 2022 to 2024). Sepsis is defined as life-threatening organ dysfunction caused by a dysregulated host response to infection. "Our previous study also found that SERINC2 functions as an endogenous protector against sepsis-associated ALI through activation of the Akt pathway." (PMID 38644501, 2024). "Taken together, our data demonstrate that Serinc2 functions as an endogenous protector against sepsis-associated ALI through suppression of STAT3, p38, and ERK pathways and activation of the Akt pathway." (PMID 35799194, 2022). "Here we, for the first time, reveal a protective role of Serinc2 in sepsis-associated ALI through inhibiting apoptosis and inflammation." (PMID 35799194, 2022). "Our findings demonstrate a protective role of Serinc2 in the lung through activating the Akt pathway, and provide novel insight into the pathogenesis of sepsis-induced ALI." (PMID 35799194, 2022).
acute lung injury (1 paper, 2025). A condition of lung damage that is characterized by bilateral pulmonary infiltrates (pulmonary edema) rich in neutrophils, and in the absence of clinical heart failure. "A study using SERINC2 knockout acute lung injury (ALI) mouse model has unveiled that Serinc2-KO mice exhibit exacerbated ALI-related pathologies after cecal ligation and puncture." (PMID 39897034, 2025).
schizophrenia (1 paper, 2024). A major psychotic disorder characterized by abnormalities in the perception or expression of reality. "The second most significant disease associated with SERINC2 variants was schizophrenia in EAs (187 SNPs with 8.2×10-8≤p ≤ 0.018 and 1.9×10-5≤q ≤ 0.049), followed by OCD in EAs (150 SNPs with 1.3×10-6≤p ≤ 0.050 and 6.5×10-5≤q ≤ 0.028)." (PMID 39902246, 2024). "This suggests that SERINC2 alleles may contribute to schizophrenia risk through accumbens GMV enlargement." (PMID 39902246, 2024). "Lastly, the disease-risk SERINC2 alleles were found to regulate the SA/TH of various cortical regions, consistent with previous reports of cortical alterations in psychiatric disorders, such as schizophrenia." (PMID 39902246, 2024).
thyroid cancer (1 paper, 2022). "In summary, our work shows a preliminary integrated analysis of the methylome and transcriptome in PTC, and a novel perspective for SERINC2 as a potential biomarker to tell indolent thyroid tumors from more aggressive thyroid cancer." (PMID 36612238, 2022). "To find the related mechanism of SERINC2 in thyroid cancer, we filtered the related genes that may substitute SERINC2 functionally based on the data from Depmap." (PMID 36612238, 2022). "The activation of the tryptophan metabolic pathway may reduce the dependency of SERINC2 in thyroid cancers." (PMID 36612238, 2022). "Therefore, we verified that SERINC2 was highly expressed in thyroid cancer cell lines." (PMID 36612238, 2022). "However, few studies about the role of SERINC2 in thyroid cancer have been conducted." (PMID 36612238, 2022). "Expression data from the TCGA dataset further showed that SERINC2 was up-regulated in thyroid cancer tissues compared with normal tissues." (PMID 36612238, 2022).
virus infection (1 paper, 2022). "According to our above research results, Serinc2 can dampen the inflammatory reaction and apoptosis in the process of LPS induced acute lung injury, and may also participate in the acute lung injury caused by virus infection and play a protective role." (PMID 35799194, 2022).
cancer (8 papers, 2020 to 2025). A tumor composed of atypical neoplastic, often pleomorphic cells that invade other tissues. "More importantly, we demonstrated a competitive relation between cancer cells and immune cells brought about by SERINC2." (PMID 39897034, 2025). "Overall, SERINC2 remodels cancer development and serine metabolism in the tumor immune microenvironment (TIME), establishing an immunosuppressive and pro-tumoral milieu." (PMID 39897034, 2025). "Six genes—HFE2, LOC339674, SERINC2, SFTA3, SOX2OT, and ACPP—emerged as the most promising candidates, supported by enrichment and survival associations across multiple cancers." (PMID 41408184, 2025). "Mechanistically, cancer cells SERINC2 preferentially competed for micro-environmental serine over CD8+ T cells and rendered T cell exhaustion." (PMID 39897034, 2025). "Positive correlation genes with SERINC2 were significantly enriched in mitotic division and the cell cycle, which are important molecular mechanisms in regulating cancer cell growth and proliferation." (PMID 32642801, 2020). "DNA methylation of cg17086398 in SERINC2 was inversely associated with myristoylated alanine-rich C-kinase substrate like 1 (MARCKSL1) expression, which is involved in migration of cancer cells." (PMID 32697766, 2020). "In numerous cancers, Serinc2 was confirmed to exert oncogenic function." (PMID 39417376, 2024). "Moreover, the investigation of data from the Cancer Dependency Map (DepMap) provided a potential pathway targeted by SERINC2." (PMID 36612238, 2022). "Furthermore, we found tryptophan metabolism as a potential pathway targeted by SERINC2 through the investigation of data from the Cancer Dependency Map." (PMID 36612238, 2022). "Researchers have been exploring the ways in which SERINC2 influences the progress of cancers." (PMID 36612238, 2022). "Our understanding of the role of SERINC2 in cancer is limited and requires further investigation." (PMID 32642801, 2020). "The Cox regression results showed that LGG was ranked statistically first among 21 different cancer types based on the FDR correlation, which further confirmed that SERINC2 is an independent predictor of OS in LGG." (PMID 32642801, 2020).
tumor (6 papers, 2020 to 2025). "Expectedly, SERINC2 knockdown impaired cell growth in vivo, evidenced by significantly reduced tumor volume and weight." (PMID 39897034, 2025). "We detected the expression of SERINC2 in human tumor samples as well as cell lines and confirmed its presence in both cell membrane and cytoplasm, as anticipated." (PMID 39897034, 2025). "In several previous studies, SERINC2 was identified as a biomarker in different tumors, for its different expression in tumors and non-tumor tissues." (PMID 36612238, 2022). "As a result, SERINC2 mRNA expression was significantly higher in tumor compared to normal tissue." (PMID 39897034, 2025). "Taken together, SERINC2 plays a pro-tumor role in vitro and in vivo." (PMID 39897034, 2025). "SERINC2 was reported to have a close correlation with tumor progression." (PMID 39897034, 2025). "Additionally, knockdown of Serinc2 inhibited tumor growth and reduced the protein expression of c‐Myc, PFKP, LDHA, and PDK1 in vivo." (PMID 39417376, 2024). "In vivo, the effect of Serinc2 knockdown on tumor growth was investigated." (PMID 39417376, 2024). "In vivo, to evaluate the function of Serinc2 on tumor growth, a xenograft mouse model was used." (PMID 39417376, 2024). "In this paper, we report SERINC2 as a potential tumor-driven indicator in PTC." (PMID 36612238, 2022). "Moreover, Serinc2 knockdown inhibited CC cell proliferation and tumor growth." (PMID 39417376, 2024). "Moreover, in vivo, low‐expression of Serinc2 restrained CC tumor growth." (PMID 39417376, 2024). "Collectively, SERINC2 inhibits CD8+ T cells infiltration to facilitate remodeling an immunosuppressive and tumor-promotive microenvironment." (PMID 39897034, 2025). "Taken together, these data indicated that low‐expression of Serinc2 inhibited cell migration, invasion, EMT, and tumor growth in CC." (PMID 39417376, 2024). "Importantly, ceramides (Cer), tumor-suppressor sphingolipids, were found to be upregulated when either SEELA or SERINC2 was knocked down." (PMID 33143730, 2020).
psychiatric diseases (1 paper, 2024). "This supports the idea that SERINC2 alleles may play key roles in the pathogenesis of these psychiatric diseases by altering cortical SA/TH too." (PMID 39902246, 2024).
SERINC2 also shares sentences with these, for which no sentence is quoted: developmental delay (2 papers); alcoholism (1); Aymé-Gripp syndrome (1); cocaine dependence (1); COVID-19 (1); Intellectual disability (1); intervertebral disc degeneration (1); ischemic stroke (1); marijuana dependence (1); melanoma (1); nervous system diseases (1); nicotine dependence (1); Potocki-Shaffer syndrome (1); substance dependence (1); thyroid tumor (1).